RN7SL835P (RNA, 7SL, cytoplasmic 835, pseudogene)
Gene: Miscellaneous RNA gene on chromosome 19 (16,907,462 to 16,907,723, forward strand). Ensembl gene ENSG00000264250.
Homologues: Orthologues: macaque Metazoa_SRP (82% identical). Paralogues in human: RN7SL819P (84% identical), Metazoa_SRP (82% identical), RN7SL474P (81% identical), RN7SL811P (81% identical), RN7SL470P (81% identical), RN7SL774P (81% identical), Metazoa_SRP (80% identical), RN7SL123P (80% identical), RN7SL154P (80% identical), RN7SL339P (80% identical), RN7SL460P (80% identical), RN7SL667P (80% identical), and 709 more.